TSC1 (TSC complex subunit 1)
Diseases named in the same sentence as TSC1 in open-access papers (continued):
Sharing a sentence is not in itself a finding about the gene and the disease.
tumor (continued). "Taken together with the distinctive spectrum of tumours seen upon deletion of Tsc1, this suggests that targeting distinct populations of endothelial cells in mice in combination with differential pathway activation impacts on the type and site of vascular tumour development." (PMID 31221668, 2019). "PTEN and Tsc1/2 are major tumor suppressors in the PI3K-PKB-TORC1 signaling network." (PMID 29677182, 2018). "A study of tumor-suppressor genes used tsc1 and tsc2 as subjects to investigate whether the Rap1 could be a link between the hamartin-tuberin complex (TSC1-TSC2) and mTORC1." (PMID 30241315, 2018). "In this case we demonstrate that this tumor is a sporadic renal AML as evidenced by somatic loss of Tsc1/2 protein in the tumor tissue compared to adjacent normal kidney without loss of FLCN protein expression." (PMID 29774133, 2018). "Loss of the tumor suppressors PTEN and Tsc1/2 results in hyperactivation of TORC1." (PMID 29677182, 2018). "The absence of both Tsc1 and Tsc2 protein expression in the tumor, however, suggests loss of Tsc1 is driving this neoplasm because Tsc2 is known to depend on Tsc1 for stability, but Tsc1 stability does not depend on the presence Tsc2." (PMID 29774133, 2018). "Loss of Tsc1/2 is considered the sufficient driver event for tumor development, and these tumors exhibit no other common genetic events." (PMID 29774133, 2018). "These generally (seven of nine tumours) co-occurred with large aberrations to TSC1/TSC2 (large deletions or CN-LOH), suggesting certain genomes may be less structurally stable." (PMID 28643795, 2017). "These RNA signatures were shared by tumours regardless of TSC1/TSC2 mutational status or presence of second hits." (PMID 28643795, 2017). "Polycystin-1 and the TSC1/TSC2 tumor suppressor complex both act to suppress the activity of mTOR." (PMID 29479522, 2017). "Biallelic inactivation of TSC2 or TSC1 is believed to represent the driving event in these tumours." (PMID 29133867, 2017). "Moreover, overexpression of PDGFRα accelerated cell proliferation and tumor growth of Tsc1- or Tsc2-null MEFs." (PMID 28903387, 2017). "Furthermore, an elevated level of p-AKT was observed in tumor tissues derived from PDGFRα-overexpressing Tsc2−/− or Tsc1−/− MEFs as compared to the control tissues." (PMID 28903387, 2017). "For example, loss of chromosome 9q34 removes tumor suppresser genes TSC1 (an mTOR pathway inhibitor), NOTCH1 (a development and stemness regulator), and GRIN1 (a calcium regulating tumor suppressor)." (PMID 27391266, 2016). "Abnormal mTORC1 signaling activation is frequently observed in variety of tumors due to gain-of-function oncogene mutations (e.g., PI3K, AKT, and Ras), and/or tumor suppressor loss-of-function mutations (e.g. PTEN, LKB1, and TSC1/2), which are crucial upstream regulators of mTORC1." (PMID 26872016, 2016). "Notably, the lung metastasis of B16 cells in Tsc1−/− mice was much severer than that in control mice, as evidenced by the increases in the lung weights and numbers of tumour colonies in the Tsc1−/− mice." (PMID 27601261, 2016). "Twenty percent of ccRCC have mutations in MTOR, TSC1, PIK3CA, and PTEN and indicates that deregulated mTOR pathways may also be critical in this tumor subtype." (PMID 27530247, 2016). "We compared rapamycin-treated Tsc1-/- and Tsc2-/- MEFs to non-treated cells, as loss of the tumor suppressor gene fully activates mTORC1 signaling in both cell types." (PMID 26872016, 2016). "Notably, all seven tumours with TSC1 or TSC2 mutations had high level of p-4EBP1 (H score=300), whereas only two of four tumours with PTEN mutations exhibited such staining." (PMID 27713405, 2016).
tumor (continued). "Loss of TSC1/2 function which enhances cell growth and promotes dysregulated metabolism leads to non-malignant tumor formation in the skin, brain, and other organs." (PMID 26483618, 2015). "Therefore, we examined the expression of TSC1/hamartin in the tumor in the protein level immunohistochemically to address the mystery of the multiple small poolings of contrast medium." (PMID 26943379, 2015). "Tumors typically showed whole chr.9 loss, likely targeting multiple tumor suppressors (i.e. INK4A, PTCH1, and TSC1) whereas the cell lines had a high frequency of both gains and losses of chromosome 9, often in association with UPD affecting either the whole chromosome or its q-arm." (PMID 25997541, 2015). "Three tumours contained mutations in ERBB2/RAS/RAF/MEK pathway members or regulators: an ARAF mutation in combination with a NCK1 mutation, a PAK1 mutation in combination with a NF1 mutation, and an ERBB2 mutation in combination with a TSC1 mutation." (PMID 26506417, 2015). "Even though previous studies with genetic targeting of IKKβ in tumor mouse models did not address the effect of IKKβ deletion on tumor angiogenesis, it has been demostrated that IKKβ can promote tumor angiogenesis by phosphorylating TSC1 and activating mTOR in tumor cells." (PMID 24955217, 2014). "Although identical TSC1 or TSC2 mutations among tumor cells are not always observed in TSC-LAM and S-LAM patients, it is clear that LAM cells are mobile; markedly, LAM cells are able to infiltrate and repopulate healthy donor lungs following transplantation." (PMID 25505789, 2014). "The ERα gene signature was used to filter expression levels in tumor samples (either ERα-positive or ERα-negative) and the mTOR associated genes Rictor, Raptor, Rheb, TSC1, TSC2, and mTOR were analyzed." (PMID 25283550, 2014). "TSC1 and TSC2 are the tumor-suppressor genes mutated in the tumor syndrome TSC (tuberous sclerosis complex) and their gene products form a complex (TSC1–TSC2) that integrates signals upstream of mTOR signaling pathway through its GAP activity towards the small G-protein Rheb." (PMID 23977024, 2013). "Further analysis of the Pten, TSC1, and TSC2 tumor suppressor genes demonstrated their loss-of-function condition resulted in severely altered blood cell homeostasis, including the abundant production of lamellocytes, specialized hemocytes involved in innate immune responses." (PMID 22911822, 2012). "A few oncogenes (e.g. phosphatidylinositol 3-kinase, activated AKT1) inhibit autophagy, while numerous tumor suppressors (e.g. BH3-only proteins, death-associated protein kinase-1, PTEN, tuberous sclerosic complex 1 and 2, TSC1 and TSC2 and LKB1/STK11) induce autophagy." (PMID 21191146, 2010). "Tumor cells showed overexpression of cyclin D1 but lacked the loss of heterozygosity of the TSC1 and TSC2 genes." (PMID 19265534, 2009). "In addition, a nude mouse model demonstrated that the tumor-promoting effect of RNF26 could be diminished by knockdown of TSC1." (PMID 38890443, 2024). "Radiological investigations confirmed the site of the tumor, and a positive expression of thyroid transcription factor 1 in the ganglion cell component, along with the absence of germline mutation in TSC1 and TSC2, led to the final diagnosis of SEGA without TSC." (PMID 39130912, 2024).
tumor (continued). "On the other hand, SEGA patients may have two independent inactivating somatic mutations in TSC1 or TSC2, and thereby, both copies of the TSC1 or TSC2 gene are lost in the cells that form the tumor, but the mutations in other patients’ cells are absent." (PMID 39410026, 2024). "Many of the most frequent actionable alterations within TMB-H tumors were within tumor suppressor pathways (PIK3CA/PTEN, CDKN2A, BRCA1/2, NF1, ATM, and TSC1/2), suggesting that many variants may be passenger rather than driver alterations in the setting of highly altered tumors." (PMID 36602798, 2023). "Finally, therapies that selectively induce cytotoxicity in TSC1- or TSC2-null tumor cells could provide a targeted approach to eliminate TSC-associated tumors without harming normal cells." (PMID 38137462, 2023). "When either the TSC1 or TSC2 gene is mutated in a way that prevents normal production of hamartin or tuberin, the growth-suppressing function of the complex is disrupted, leading to overactivation of mTOR pathway signaling and uncontrolled cell growth, which results in tumor formation." (PMID 38137462, 2023). "TSC1 and TSC2 are classified as tumor suppressor genes and function according to Knudson’s two-hit hypothesis, which requires both alleles to be damaged for tumor formation." (PMID 37232723, 2023). "The destruction of TSC1/TSC2 tumor suppressor function may contribute to the occurrence of tumor." (PMID 35572821, 2022). "These comprised two truncating pathogenic variants—RB1 R255* and TSC1 R786*, one missense probable damaging variant—VHL tumor suppressor R58W, and four splice variants of unknown significance in ETS2 transcription factor, SGK1 serum/glucocorticoid regulated kinase 1, AXL RTK and MIB1." (PMID 31258848, 2019). "In addition, the TSC1 homozygous pathogenic variant (on chromosome 9) detected on metastatic material, was not present in the primary tumor." (PMID 31443247, 2019). "Thus, the differential strength of PKB signaling opposing the activity of FoxO in the context of loss of Tsc1 and PTEN points to the FoxO activation status as the key determinant of the malignant potential of tumors caused by the loss of these tumor suppressors." (PMID 29677182, 2018). "In addition to TSC1/TSC2, we hypothesized that lesions may acquire mutations in other genes, including those that affect tumour growth." (PMID 28643795, 2017). "Similarly, tumours with two truncating TSC1 mutations showed a lower level of TSC1 mRNA compared to non-TSC tissue (pair-wise Welch’s t-tests; FDR-adjusted P=0.03)." (PMID 28643795, 2017). "Furthermore these observations suggest that there is likely a specific cell type (currently unknown) that is resident in the early kidney that is sensitive to the tumor and growth promoting effects of TSC2 or TSC1 loss." (PMID 27494029, 2016). "Therefore, Tsc1 may play an extrinsic role in the suppression of tumour growth via regulation of the cellularity of NK cells." (PMID 27601261, 2016). "Interestingly, Tsc1/2 and Flcn are tumor suppressors, whereas Tfe3 is a protooncogene." (PMID 23582324, 2013). "NF2, TSC1, and PTPN12 were positively selected, indicating a potential tumour suppressing function for these genes, while MYC, HRAS, and PTPN11 were negatively selected, highlighting their oncogenic role." (PMID 40650785, 2025). "AKT phosphorylated by the PI3K complex tuberous sclerosis 1/2 (TSC1/2), initiates the AMPK pathway as a tumor suppressor by blocking mTOR activation." (PMID 40688079, 2025). "They showed that NF1, TSC1, and TGF-β RII are important tumour suppressors that regulate immune composition, and their loss enhances IL6-JAK3-STAT3/6 inflammatory pathways, increasing LAG3 + CD8 and CD4 T cells." (PMID 40650785, 2025). "The depletion of TSC1, a negative regulator of mTORC1, has been shown to lead to TAM reprogramming and the suppression of tumor growth." (PMID 39766137, 2024).
tumor (continued). "We also observed enrichment of sgRNAs targeting CDKN1B, PTEN, TSC1 and TSC2 in both cell types, suggesting deletion of these tumor suppressors provides a survival advantage." (PMID 38480701, 2024). "The present investigation has successfully identified several novel oncogenic drivers and tumor suppressors specific to SCLC, including Tsc1 (tuberous sclerosis complex 1)." (PMID 38473324, 2024). "Seven genes passing these filters were involved in various aspects of tumour biology, including cell survival and DNA repair (CASP9, NDRG1, and XPA), mTOR signalling (TSC1), and transcription and RNA processing (ETV6, ISY1, and SMAD2)." (PMID 39660592, 2024). "It is worthwhile to note that, some tumor suppressors including LKB, TSC1, and TSC2 also exhibit tumor cell promotion function especially in some metabolic stresses conditions." (PMID 37543638, 2023). "Physiologically, the inhibitors of mTORCs are Tuberous Sclerosis Complex 1 (TSC1) and TSC2 proteins, which are important tumor suppressors that inhibit cell growth." (PMID 37443747, 2023). "In this study, 105 immune-related genes from tumor gene sets were identified as IRPGs in PAAD patients by the univariate Cox analysis, and 4 genes of IRPGs, RHOF, CEP250, TSC1, and KIF20B were then used to construct the IRPM." (PMID 38203311, 2023). "We also observed enrichment of sgRNAs against CDKN1B, PTEN, TSC1 and TSC2 in both cell types, suggesting deletion of these tumor suppressors provides a survival advantage." (PMID 37502925, 2023). "Because the TSC1/TSC2 complex is the principal suppressor of mTORC1 signaling and hyperactivated mTORC1 is the main reason for tumor formation in TSC disease, Tsc1 − / − or Tsc2 − / − MEFs and TSC samples are excellent models for the study of mTORC1 signaling." (PMID 36217202, 2022). "The phosphorylation curve shows that the mTOR pathway is activated by the disrupted function of the TSC1/2 complex, which proves that the carcinogenic lineage of PEComa is a unique TSC2-related tumor." (PMID 35928867, 2022). "In cells, mTORC1 is negatively regulated by a heterodimer complex consisting of TSC1 and TSC2, which are the products of the tumor suppressor genes Tsc1 and Tsc2." (PMID 34199299, 2021). "Furthermore, mutations in TSC1, TSC2, JAK1, and DAXX appeared at the level of ATC, making it likely that some of these genetic events influenced the development of this undifferentiated tumor type - although only the TSC1 and DAXX mutations were carried along to the metastatic ATC component." (PMID 35582231, 2020). "The TSC-1 and TSC-2 proteins form a complex and function as tumor suppressors by inhibiting mTORC1 kinase." (PMID 32397669, 2020). "Some well-characterized tumor suppressors, such as PTEN and TSC1/2, negatively regulate the protein kinase mTOR and induce autophagy." (PMID 30987661, 2019). "Tuberous sclerosis complex 1 (TSC1), TSC2, and PTEN (phosphatase and tensin homolog) tumor suppressors are major negative regulators of mTOR signaling pathway." (PMID 29362480, 2018). "Targeted NGS of MTOR, TSC1 and TSC2 genes was performed on DNA extracted from formalin-fixed paraffin-embedded primary tumor and hepatic metastasis, and the patient’s peripheral blood (TruSeq Custom Amplicon Low Input; Illumina)." (PMID 29764404, 2018). "Energy stress, through activation of AMPK is also upstream of TSC1/TSC2, where AMPK-dependent phosphorylation of TSC2 on Thr1227 and Ser1345 activates the TSC1/TSC2 tumour suppressor, leading to mTORC1 inhibition." (PMID 29547541, 2018).
tumor (continued). "Genes that negatively interact with both TSC1 and TSC2 represent potential therapeutic targets (i.e. drugs inhibiting a negative interactor would be predicted to suppress the growth of tumor cells while leaving phenotypically normal cells unaffected)." (PMID 29343513, 2018). "AMPK activated by AICAR has been proposed to exhibit an antitumorigenic effect because it is the major signaling network of tumor-suppressor genes, such as LKB1 and TSC1/2." (PMID 29117108, 2017). "Many of the proteins that negatively regulate mTOR are tumor suppressors, such as PTEN, AMPK, and TSC1/2." (PMID 27034171, 2016). "The TSC1/2 complex, a heterodimer of TSC1 and TSC2, functions as a tumor suppressor by inhibiting mTORC1." (PMID 26000908, 2015). "Results demonstrate that Rictor, TSC1, and TSC2 (all activators of mTORC2 signaling) have higher expression levels in ERα+ tumor samples compared to ER−." (PMID 25283550, 2014). "The TSC1/2 complex inhibits TOR signaling, acting as a tumor suppressor in vertebrates and regulating cell growth." (PMID 23144631, 2012). "The cytokines secreted by the few vGPCR-expressing tumor cells activate in neighboring cells multiple pathways (including AKT, ERK, p38 and IKKβ) that, in turn, converge on TSC1/2, promoting mTOR activation, HIF upregulation, and VEGF secretion." (PMID 21559457, 2011). "In tumor-like cells, ERK phosphorylates TSC2 leading to the dissociation of TSC1/TSC2 complex with subsequent up-regulation of mTORC1." (PMID 21200439, 2010). "Last, ARG1 was reported to promote HCC growth and metastasis by enhancing tumor cell epithelial-mesenchymal transition, whereas ectopic expression of ARG1 in a Tsc1/Pten DKO model suppressed HCC development by consuming arginine, and limiting arginine led to tumor cell growth arrest and apoptosis." (PMID 41512056, 2026). "Genetic ablation of TSC1, a negative regulator of mTORC1 in TAMs, inhibits tumor growth independent of adaptive immunity." (PMID 41417432, 2025). "As expected, we detected positive enrichment of gRNAs targeting tumor suppressors, PTEN, TSC1, and TSC2, in both DMSO- and imlunestrant-treated cells on days 14 and 31, indicating that loss of PTEN and TSC1/2 enhance tumor cell growth without and with imlunestrant treatment." (PMID 40327396, 2025). "The anti-LAG3/PD-L1/Paclitaxel treatment showed the most significant metastasis reduction from tumors with NF1, TSC1, or TβRII inactivation but not from the 4T1-C1 control tumor." (PMID 38997291, 2024). "As expected, knockout (KO) of Nf1 or Tsc1 or Tgfbr2, but not Nf2, increased the number of spontaneous lung metastatic nodules and increased the primary tumor size." (PMID 38997291, 2024). "Thus, CHUK, IKBKB gene products, and co-chaperones FKBP5 (FKBP51), TSC1, and TSC2 interact with Hsp90 and behave like tumor suppressors, while AKT1 shows oncogenic behavior and is involved in the enhanced activity of many signaling pathways." (PMID 39337357, 2024). "Together, our data suggest that NF1, TSC1, or TβRII inactivation resulted in a tumor cell non-autonomous immune suppressive microenvironment that is potentially mediated by LAG3+ CD8 T and CD4 T cells." (PMID 38997291, 2024). "From the results, we noticed that tumor cells highly expressed AUP1 significantly correlated with proliferation marker (MCM2, MCM6), PI3K-AKT-MTOR pathway (Akt1, TSC1, mTOR, Foxo1), and autophagy signaling (Atg3, Atg4B, Atg4D, Atg7, Atg9A, Atg16L1) in IDH wildtype tumor cells." (PMID 37029364, 2023). "The TSC1 and TSC2 genes are classified as tumor suppressor genes and function according to Knudson’s two-hit hypothesis, which means that both alleles must be damaged for tumor formation." (PMID 37232723, 2023). "This process is caused by the overexpression of HIF1-α, mediated by the mTOR pathway through the alteration of tumor suppressor genes, such as serine/threonine kinase 11 STK (STK11), TSC complex subunit 1 (TSC1), TSC complex subunit 2 (TSC2) and AKT serine/threonine kinase 1 (AKT1)." (PMID 37239099, 2023).